PINK1 (PTEN induced kinase 1)
Diseases named in the same sentence as PINK1 in open-access papers (continued):
Sharing a sentence is not in itself a finding about the gene and the disease.
pulmonary fibrosis (continued). "Interestingly, the pro-fibrotic cytokine TGF-β may be protective to lung epithelial by promoting PINK1 expression and attenuating AEC apoptosis that drives lung fibrosis." (PMID 26370974, 2015). "Consistently, in the present study, we found that OGG1 could negatively regulate PINK1/Parkin expression during pulmonary fibrosis both in vivo and in vitro, providing evidence that OGG1/PINK1/mitophagy axis acted as a critical mediator against pulmonary fibrosis through." (PMID 38822247, 2024). "In light of the findings above, we hypothesized that upregulation of PINK1 by TGF-β1 represents an epithelial cell pro-survival response, and that inhibition of mitophagy through genetic elimination of Pink1 would worsen experimental lung fibrosis in response to bleomycin." (PMID 25785991, 2015). "Similarly, in the BLM-induced pulmonary fibrosis model mice, TA293 did not suppress PINK1 or Parkin expression, but mitoTA293 did." (PMID 34573030, 2021).
heart failure (41 papers, 2014 to 2026). Inability of the heart to pump blood at an adequate rate to meet tissue metabolic requirements. "For example, pressure overload-induced heart failure in mice is associated with reduced PINK1-Parkin mitophagy signaling, contributing to accumulation of defective mitochondria." (PMID 41007357, 2025). "PINK1 knockout mice were more susceptible to overload-induced heart stress and consequent heart failure than wild type mice." (PMID 32257551, 2020). "PINK1-deficiency mice increased heart failure more rapidly in response to pressure overload than wild-type mice, and developed the susceptibility of the heart to I/R injury ex vivo." (PMID 27148058, 2016). "In heart failure models, a pathological shift from AMPKα2 to AMPKα1 impairs mitophagy and exacerbates mitochondrial dysfunction, whereas restoration of AMPKα2 enhances mitophagy via the PINK1/Parkin pathway and reduces ROS, effects that are lost in PINK1/Parkin-deficient systems." (PMID 40860364, 2025). "For example, Pink1 protein levels are significantly reduced in human end-stage heart failure, and Parkin deficiency leads to the accumulation of dysfunctional mitochondria in cardiomyocytes, the development of heart failure, and, ultimately, an increase in myocardial infarction size in mice." (PMID 40507126, 2025). "Interestingly, the PINK1 gene also has been recently associated with heart failure." (PMID 25147748, 2014). "Recent studies have identified SIRT1 as a key modulator of autophagy, including its role in alleviating mitochondrial damage via the PINK1‐Parkin autophagy pathway, thereby protecting against post‐myocardial infarction remodelling in heart failure models." (PMID 40026072, 2025). "PTEN-induced kinase 1/Parkin RBR E3 ubiquitin-protein ligase (Pink1/Parkin) is thought to be an important component that mediates mitochondrial autophagy in cardiomyocytes and is intimately involved in heart failure." (PMID 40507126, 2025). "In the present study, the expression of PINK1 protein was significantly decreased and Parkin expression was significantly increased in the myocardium of heart failure mice." (PMID 40076760, 2025). "In the heart failure group, PINK1 protein expression was significantly down-regulated, Parkin and BNIP3 protein expression were significantly up-regulated, and SKQ1 and aerobic exercise significantly down-regulated Parkin and BNIP3 protein expression." (PMID 40076760, 2025). "Ginsenoside Rg1 inhibits cardiac remodeling in heart failure through SIRT1/PINK1/Parkin-mediated mitochondrial autophagy." (PMID 39141645, 2024). "Taken together, these data confirm that mesaconine exerts a potent therapeutic effect against cardiac dysfunction and remodeling in DOX-induced heart failure mice through targeting PINK1-dependent autophagic clearance of damaged mitochondria." (PMID 37124193, 2023). "Graf1 phosphorylation on PINK1-dependent sites is dysregulated in human heart failure, and cardiomyocyte-restricted Graf1 depletion in mice blunts mitochondrial clearance and attenuates compensatory metabolic adaptations to stress." (PMID 38081847, 2023). "Evidence of this is the decrease in PINK1 activity in patients with heart failure, as well as the development of heart failure shown in a mouse model with PINK1 deficiency." (PMID 36499064, 2022). "Activate mitophagy via the PINK1/Parkin pathway and protect cardiac function in pressure overload-induced heart failure." (PMID 36034426, 2022). "In TAC-induced heart failure mice, AMPKα2 can enhance PINK1/Parkin-mediated mitophagy to protect cardiomyocytes through PINK1 phosphorylation." (PMID 35528513, 2022). "In a study on the improvement of cardiac function by berberine, it was found that the coordinated action of berberine and the Pink1/Parkin pathway enhances mitochondrial phagocytosis and protects patients with heart failure." (PMID 36555691, 2022).
heart failure (continued). "Research from other and ours support the notion that PINK1/Parkin mitophagy is cardiac-protective, an adaptive response, during sepsis as well as other pathological conditions of heart failure." (PMID 35265609, 2022). "PINK1/Parkin was significantly downregulated in TAC-induced heart failure, while BBR upregulated PINK1/Parkin-mediated mitophagy." (PMID 36132224, 2022). "Animal experiments confirmed that berberine activated mitophagy via the PINK1/Parkin pathway and protected cardiac function in pressure overload-induced heart failure." (PMID 36034426, 2022). "Phosphorylation of Ser495 in PINK1 by AMPKα2 is essential for efficient mitophagy to prevent the progression of heart failure." (PMID 35740401, 2022). "It has been shown that phosphorylation of Ser495 in Pink1 by AMPKα2 is necessary for effective mitotic inhibition of the progression of heart failure." (PMID 36555691, 2022). "Cardiac hypertrophy was also identified as a consequence of PINK1 knockout in mice, and PINK1 protein is drastically decreased in heart failure." (PMID 33544154, 2021). "PINK1 KO mice developed left ventricular dysfunction and cardiac hypertrophy, which led to pressure overload-induced heart failure." (PMID 33957982, 2021). "AMPKα2 in cardiomyocytes phosphorylates PINK1 at ser495 and activates PINK1-Parkin-mediated mitophagy to prevent heart failure." (PMID 34751247, 2021). "However, it is uncertain whether PINK1 downregulation is the cause or effect of heart failure." (PMID 32257551, 2020). "The activation of AMPKα can enhance PINK1-dependent mitophagy and provide protection against heart failure deterioration." (PMID 32312955, 2020). "PINK1 is generally downregulated in individuals with heart failure, indicating a reduction in mitophagy levels." (PMID 32257551, 2020). "Notably, activating AMPK an energy-sensing kinase often suppressed in hypertension can stimulate protective mitophagy; AMPKα2 was shown to phosphorylate PINK1 and promote Parkin recruitment, preventing development of heart failure in a pressure-overload model." (PMID 41007357, 2025). "There are studies reporting that Nuanxinkang can prevent the development of myocardial infarction-induced chronic heart failure by promoting PINK1/Parkin-mediated mitophagy and ginsenoside Rg1 can protect against cardiac remodeling in heart failure via SIRT1/PINK1/Parkin-mediated mitophagy." (PMID 38716483, 2024). "Together, our findings suggest that the cardioprotective effects of mesaconine appear to be dependent on the activation of PINK1-induced mitophagy and that mesaconine may constitute a promising therapeutic agent for the treatment of heart failure." (PMID 37124193, 2023). "Collectively, these findings indicate that dysregulation of GRAF1 expression or activity may exacerbate heart failure and possibly other disorders that result from defects in PINK1/Parkin-mediated mitochondrial quality control." (PMID 38081847, 2023). "Interestingly, it has also been reported that AMPK can activate mitophagy via PINK1 phosphorylation in the heart failure model of mammals." (PMID 35624756, 2022). "PINK1 protein levels are markedly reduced in end-stage human heart failure." (PMID 35740401, 2022). "However, in addition to the FUNDC1-mediated receptor-dependent autophagy, the PINK1/Parkin pathway-mediated receptor-independent mitophagy in heart failure deserves further attention." (PMID 36132224, 2022). "Additionally, pharmacological upregulation of PINK1/Parkin-mediated mitophagy was found to protect against heart failure." (PMID 35330106, 2022). "Therefore, the AMPKα2-mediated phosphorylation of PINK1 at Ser495 stimulates the PINK1–Parkin–SQSTM1 signaling implicated in cardiac mitophagy, and these events are essential for preventing the progression of heart failure." (PMID 35011593, 2021). "In vivo studies using animals confirmed the role of PINK1 in heart failure." (PMID 32257551, 2020).
heart failure (continued). "BAG3 functions upstream of Parkin, and BAG3 knock-down reduced PINK1/Parkin-mediated mitophagy and impaired the clearance of defective mitochondria, thus increasing levels of toxicity within the cells and subsequent cell death in the context of heart failure." (PMID 32257551, 2020). "Indeed, it has been demonstrated that PINK1 protein levels are significantly reduced in human end-stage heart failure and that PINK1 activity is essential for correct postnatal myocardial development, suggesting that mitophagy impairment contributes to the pathological process of heart disease." (PMID 37124193, 2023). "In addition, PINK1 protein levels are markedly reduced in end-stage human heart failure." (PMID 30333475, 2018). "Therefore, Pink1/Parkin-mediated mitochondrial autophagy plays an important role in promoting cardiomyocyte survival and could be a potential strategy for the treatment of heart failure." (PMID 40507126, 2025). "We provide strong evidence that GRAF1 is necessary for mediating PINK1/Parkin-dependent mitochondrial homeostasis in the heart following an adrenergic challenge and that GRAF1 is dysregulated in human heart failure." (PMID 38081847, 2023). "AMPKα2 can enhance PINK1/Parkin-mediated mitophagy through PINK1 phosphorylation, thereby protecting cardiomyocytes in TAC-induced heart failure mice." (PMID 35528513, 2022). "Notably, PINK1 knockdown significantly inhibited Parkin-mediated mitochondrial ubiquitination and counteracted the beneficial effects of BBR on heart failure." (PMID 36132224, 2022).
diabetes (40 papers, 2014 to 2025). "Conversely, in the control group, elevated PINK1 expression was associated with diabetes mellitus and subjects with RBD." (PMID 38711597, 2024). "Although the prior consensus regarding mitophagy in diabetes was that elevations in mitophagy markers like PINK1‐PARKIN in skeletal muscle were associated with the onset of T2D, recent studies suggest increased mitophagy actually serves as a protective response for the onset of insulin resistance." (PMID 41214862, 2025). "Overall, our data strongly suggest that exacerbated Pink1-dependent mitophagy (together with normal mitochondrial biogenesis) underlies the reduction of mitochondrial contents at the outer retina of Ins2Akita/+ mice during the early stages of diabetes." (PMID 31661466, 2019). "Moreover, PINK1 deficiency worsened diabetes-induced intrarenal ROS formation." (PMID 37928264, 2023). "The PINK1/Parkin pathway plays a central role in mitophagy regulation, especially under high glucose conditions seen in diabetes." (PMID 39859520, 2025). "In conclusion, our findings suggest the suppressed PINK1/Drp1-mediated mitophagy is responsible for the impairment of osteogenic differentiation in diabetes." (PMID 39758822, 2025). "In a rat model of STZ diabetes, in 4-week after diabetes induction (early diabetes), PINK1 was increased in the renal cortex." (PMID 41567637, 2025). "In this study, we revealed that the suppressed PINK1/Drp1-mediated mitophagy is a molecular pathway responsible for impaired osteogenic differentiation in diabetes." (PMID 39758822, 2025). "Comorbidities such as diabetes aggravate IRI by inhibiting the PINK1/Parkin, which makes the renal tubules more sensitive to ischemic injury." (PMID 41451126, 2025). "A recent study found that STING1/PINK1-mediated mitophagy is impaired in the kidney in a diabetes mouse model induced by HF-D combined with STZ." (PMID 38803440, 2024). "Collectively, these data emphasize the potential importance of PINK1 in maintaining mitochondrial homeostasis and cell function across different cell types within the diabetic glomerulus." (PMID 37928264, 2023). "In an early diabetes mouse model expression of PINK1 was significantly increased in the kidney cortex, which suggests that mitophagy is increased in early diabetes." (PMID 36766754, 2023). "PINK1-knockout mice showed more severe diabetes-induced tubular injury, interstitial fibrosis, and albuminuria." (PMID 37928264, 2023). "And antioxidants, such as NAC and natural COA water, control mitochondrial ROS by diabetes-induced damage and negatively regulate the Parkin-mediated mitophagy function by PINK1 in the mitochondrial outer membrane." (PMID 37134105, 2023). "LIPUS also potently activates PINK1/Parkin-dependent mitophagy and plays a role in promoting β-cell resistance to diabetes-related hyperlipotoxicity." (PMID 36499213, 2022). "By generating tool compounds and testing phosphorylation sites in PINK1 and Parkin, the field is getting closer to a molecular understanding of how dysregulation of this pathway could lead to dopaminergic neuron loss in PD or poor mitochondrial clearance in diabetes." (PMID 35754955, 2022). "Since our in vivo data suggest a role for Pink1 in diabetes-induced mitophagy, we next evaluated the involvement of this pathway in HG- and LG-mediated mitophagy." (PMID 31661466, 2019). "In this study, we not only confirmed the role of mitochondrial dysfunction in DCM, but also found the importance of mitophagy, especially the PINK1-Parkin pathway, which is also expected to be a new target for the treatment of multiple complications of diabetes." (PMID 39000117, 2024). "PINK1 and parkin have also been shown to be upregulated in the vasculature of obese and diabetic mice, so research to elucidate the interplay between PINK1/parkin, mitophagy, diabetes and PD may help to clarify our understanding." (PMID 36860818, 2023).
diabetes (continued). "FOXO3A, Plk3, Parkin, and PINK1 genes may be used in future precision medicine as biomarkers for diabetes." (PMID 37134105, 2023). "Diabetes induced an increase in PINK1 expression in the kidneys." (PMID 37928264, 2023). "However, as diabetes duration increases, Pink1-dependent mitophagy deteriorates, leading to the build-up of mitochondria primed for degradation in DR." (PMID 31661466, 2019). "However, FL-Pink1 stabilization and Parkin levels were strikingly increased, suggesting that Pink1-primed mitochondria are ineffectively cleared and accumulate in the retina at advanced stages of diabetes." (PMID 31661466, 2019). "Utilizing PPI topology analysis, mTOR, Parkin, AKT, Beclin-1, P62, LC3A, Pink-1, and PI3K were established as key targets for diabetes treatment." (PMID 39211336, 2024). "Metformin significantly upregulated the levels of p-PINK1, PINK1, Parkin, and p62 and increased the ratio of LC3-II/LC3-I in the brain tissue of diabetes rats with CI/R injury." (PMID 38348222, 2024). "Indeed PINK1-dependent mitophagy in both Müller cells and photoreceptors was exacerbated within the first 2 months of diabetes, while a significant impairment of the pathway was reported in the advanced stages of neurovascular dysfunction (8 months of diabetes)." (PMID 34234681, 2021). "Further research on PINK1/Drp1-mitophagy pathway and its agonists, such as BMP9, is a promising way to explore the potential pathogenesis and therapeutic strategy for osteoporosis in diabetes." (PMID 39758822, 2025). "In diabetic mice, serum creatinine and urea nitrogen levels were significantly increased compared to control mice, and the absence of PINK1 further exacerbated diabetes-induced kidney dysfunction." (PMID 37928264, 2023). "Significant decrease in mitolysosome, higher PINK1 stabilization on the mitochondria, and substantial increase in Parkin suggested that PINK1 primed mitochondria are not cleared by mitophagy in later stages of diabetes." (PMID 34440882, 2021). "The gene expression of mitophagy markers PINK1 and PARK2 by qPCR was decreased in peripheral blood samples taken from individuals with diabetes, regardless of DKD status, compared to NDC (data not shown)." (PMID 36010558, 2022).